MSH6 (mutS homolog 6)
Diseases named in the same sentence as MSH6 in open-access papers (continued):
Sharing a sentence is not in itself a finding about the gene and the disease.
tumor (continued). "Both dMMR tumors showed impaired immunoreactivity, with one tumor displaying a simultaneous loss of the MLH1/PMS2 heterodimer and the other showing isolated MSH6 loss." (PMID 40415014, 2025). "Three patients were suspected to have cMMRD based on somatic tumor variants in the MLH1, MSH6, and PMS2 genes combined with the high mutational burden observed in their tumors." (PMID 40980447, 2025). "Limited data support the extension of surveillance intervals for carriers of pathogenic variants MSH6 and PMS2, who are proven to have lower cumulative CRC incidences, possibly due to this different tumour biology." (PMID 40241188, 2025). "Case 6, which had the highest number of SNVs, had missense mutations in ATM, POLE and BRCA2, as well as known pathogenic mutations from ClinVar in MSH6, RAD50, APC and NF1, likely explaining the high mutational load in this tumor." (PMID 40670673, 2025). "MSI analysis revealed instability in BAT26 in the MLH1/PMS2-deficient tumor and at D17S250 in the MSH6-deficient tumor." (PMID 40415014, 2025). "The fact that there is also a reduced signal in LS tumours suggests that MSI-based detection of MMRd in ECs from LS patients with MSH6 lesions is particularly difficult." (PMID 39682157, 2024).
tumor (continued). "This analysis provided direct in vivo support for MSH6 homopolymer frameshift switching during tumor evolution." (PMID 38956208, 2024). "These considerations along with the Case 1 patient’s LS phenotype and variable tumour MMR status despite homozygosity for MSH6 c.3226C>T meant the diagnosis remained uncertain." (PMID 38789506, 2024). "We indeed found sequential loss and restoration of the C8 homopolymer reading frame, suggesting that the MSH6 homopolymer had dynamically contracted and expanded during tumor growth." (PMID 38956208, 2024). "The responder in Group B2, who received gemcitabine, cisplatin, and S-1 with nivolumab, had microsatellite instability (MSI)-high tumors with a high tumor mutation burden (TMB) and germline MSH6 mutation." (PMID 39249118, 2024). "In one patient, with a MSS tumor according to NGS, a frameshift mutation was detected in mutS homolog 6 (MSH6), encoding for the mismatch repair protein MSH6." (PMID 38642130, 2024). "We also sought to replicate this finding in the cohort of CRCs from LS patients (n = 35) by analysing median marker VAFs from tumours with MSH6 lesions, normalised to tumours with germline defects in other MMR genes." (PMID 39682157, 2024). "A MSH6 missense mutation c.2407G > C (p.D803H) of uncertain significance (VUS) was also identified via TEMPUS and the tumor was found to be microsatellite stable by IHC proxy with retained expression of MSH6." (PMID 39707480, 2024).
tumor (continued). "In family E, the presence of NM_000179.3:c.3226C>T in the MSH6 gene (reference sequence NM_000179.3) was confirmed in the proband’s father by Sanger sequencing, followed by IHC in her tumor tissue." (PMID 39436407, 2024). "For example, SLS116 showed solitary loss of MSH6 expression initially and when repeated internally showed loss of MLH1/PMS2 that was related to tumor MLH1 methylation." (PMID 37101184, 2023). "MSH6 (stained due to the detected molecular alteration, see molecular findings below) was retained in tumor cells." (PMID 37401932, 2023). "No inactivation of the remaining MSH6 wildtype allele was identified, and both tumors demonstrated retained/intact expression of MSH6 protein in tumor nuclei by immunohistochemistry." (PMID 38079020, 2023). "Three (Cases #3, 12, and 13) of four MSH6-mutant tumors had MSH6 loss only, but both MSH6 and PMS2 losses were also found in one MSH6-mutant tumor (Patient #8)." (PMID 34848827, 2022).
tumor (continued). "High TILs scores were significantly associated with women (P=0.027), smaller tumor size (P=0.007), high MLH1 expression (P=0.021), high MSH6 expression (P=0.003), pMMR (P=0.003), and PD-L1 expression (P<0.05)." (PMID 35865481, 2022). "In different tumor samples of TCGA project, the MSH6 genetic alteration status was gained from cBioPortal." (PMID 34941572, 2021). "Regions that encode gene products (proteins) involved in tumor suppression (e.g., TGFBR2), cellular growth, DNA repair (e.g., MSH3, MSH6), and apoptosis (e.g., BAX) contain repeat sequences, and genetic changes are likely to occur in these regions." (PMID 34185173, 2021). "In recent years, the close relationship between MSH6 and tumor has also been continuously discovered." (PMID 34941572, 2021). "At the genetic level, tumor mutation burden and alterations in DNA damage response and repair genes including ATM, ERCC2, BRAC-2, FANCA, MSH6, and POLE can to some extent predict the response of ICIs in specific cancer types." (PMID 33791296, 2021). "The only MSS tumor with an MMR mutation was P592, which had a somatic mutation in MSH6 as we describe in more detail later." (PMID 34488871, 2021). "Interestingly, according to the surgical pathology report of the resected tumour, patient 3 had a rare loss of MSH6 expression which is known to increase neoantigen presentation and could explain the unusually high amount of CD45-positive immune cells in the tumour." (PMID 33479301, 2021).
tumor (continued). "Given that cyclin F, RRM2, and SPDL1 are considered GIN-related proteins, we also analyzed their expression in relationship to tumor aneuploidy score and fraction genome altered (TCGA cohort) or MSH6 protein level (our cohort)." (PMID 33670609, 2021). "A large number of studies have confirmed that MSH6 can promote tumor genesis and development through the interaction with histone H3Kme36, chromatin complex effects, and genomic microsatellite instability and other mechanisms." (PMID 34941572, 2021). "The results of this study demonstrated that, compared with normal tissues, total MSH6 protein was highly expressed and phosphorylated at S830 and S227 sites in MutS_III domain in primary tumor tissues." (PMID 34941572, 2021). "In this study, for the first time, we analyzed the correlation between MSH6/2 and PD-L1 mRNA expression levels and clinical and pathological factors related to tumor proliferation and invasiveness using tissue from human NFPAs." (PMID 32325698, 2020). "In other words, in NFPAs, tumor proliferation is promoted by the reduction of the expression of MSH6/2." (PMID 32325698, 2020). "The relatively modest numbers of cases in certain groups (e.g., the MSH6-deficient group) and poor availability (and sometimes low quality due to formalin-fixed paraffin-embedded (FFPE)-origin) of tumor samples are among the limitations." (PMID 32660107, 2020). "The tumor was microsatellite stable and had normal MSH6 expression, and along with benign in silico prediction, the variant has a low probability of being pathogenic." (PMID 33193653, 2020). "Mismatch repair genes mutS homologs 6/2 (MSH6/2) expressions are involved in tumor growth and programmed cell death 1 ligand 1 (PD-L1) expression in tumor immunity, but the direct association with pituitary adenomas (PAs) is not well understood." (PMID 32325698, 2020).